MPO (myeloperoxidase)
Diseases named in the same sentence as MPO in open-access papers (continued):
Sharing a sentence is not in itself a finding about the gene and the disease.
colitis (continued). "The data demonstrate that HU308 has a significant therapeutic effect on DSS-induced colitis in mice, as evidenced by the restoration of colon length, reduction in MPO activity in both the colon and spleen, normalization of plasma GLP-1 levels, and reduction in spleen/body weight ratio." (PMID 39682761, 2024). "Contrary to previous pharmacological antagonist studies targeting MPO, MPO-deficient mice showed no protection from experimental colitis during cyclical DSS-challenge." (PMID 38673843, 2024). "In addition, colonic MPO activity was significantly increased in the inflamed colons compared to the non-colitis control group." (PMID 39334888, 2024). "We hypothesized that blocking MPO would attenuate acute colitis and prevent the development of chronic colitis by limiting bystander tissue damage." (PMID 39133648, 2024). "Furthermore, it decreased the levels of myeloperoxidase, nitric oxide, and malondialdehyde activities while increasing the glutathione content in the colon tissue of colitis-affected animals." (PMID 38790796, 2024). "While we have previously reported that MPO inhibition via pharmacological intervention using either cyclic nitroxides (4-methoxy-TEMPO) or 2-thioxanthines (AZD3421) ameliorates DSS-induced colitis, we now report that MPO KO mice showed poor colitis outcomes during acute experimental colitis." (PMID 38673843, 2024). "It is possible that MPO gene deletion may impact the immunological gut milieu and this could have altered the clinical outcome of experimental colitis." (PMID 38673843, 2024). "Furthermore, DSS-induced colitis mice exhibited significantly higher myeloperoxidase (MPO) activity in comparison to the CON group." (PMID 38380090, 2024). "In addition, the gamma-oryzanol diet significantly decreased the activity of colon myeloperoxidase, an enzymatic biomarker for neutrophilic granulocytes, in dextran sulfate sodium-induced colitis in mice when compared with a normal food diet." (PMID 38337717, 2024). "After day 5, when colitis was first induced, therapeutic treatment with mangiferin reduced the levels of superoxide dismutase (SOD), reduced glutathione (GSH), myeloperoxidase (MPO), and malondialdehyde (MDA), and alleviated colitis symptoms such as (weight loss and diarrhea)." (PMID 39479608, 2024). "Similar results were obtained in DSS-induced colitis mice, as 4-methyl-esculetin administered orally at 25 mg/kg daily, improved microscopic parameters, reduced MPO activity, lowered colonic IL-6 levels, and prevented GSH depletion compared to the DSS-control group 562." (PMID 39494333, 2024). "The observed changes to the gut microbiome and the relative abundance of certain genera following MPO deletion may have influenced the outcome of DSS-induced colitis when compared to the pharmacological blockage of MPO." (PMID 38673843, 2024). "Interestingly, a recent study showed that H2S donor significantly inhibited PAD4, Cit-H3 and MPO expression in TNBS-induced colitis rats." (PMID 39170617, 2024). "The experimental findings demonstrated that FMT from all four groups of donors decreased the increasing DAI in mouse colitis, downregulated the levels of inflammatory biomarkers MPO and EPO, and regulated homeostasis of colonic inflammatory cytokines and the intestinal barrier." (PMID 38990027, 2024). "Similarly, the oral administration of Butyricicoccus B pullicaecorum has shown a significant protective effect in reducing intestinal myeloperoxidase, tumor necrosis factor α, and interleukin-12 levels in colitis." (PMID 39457690, 2024). "Similarly, the measurement of the inflammatory neutrophil marker MPO indicated an amelioration in colitis, particularly after anti-miR-21 treatment." (PMID 39224018, 2024). "Moreover, we revealed anti-inflammatory activity of EMPA in in vivo model of acute colitis, in which the therapy resulted in the decrease of MPO activity." (PMID 37086302, 2024).
colitis (continued). "Fish‐scale collagen peptide showed anti‐inflammatory effects on colitis mice by reducing myeloperoxidase (MPO)‐dependent activation of inflammatory cells, which can also inhibit the activation of the nuclear factor NF‐κB pathway and serum active monocyte chemotactic protein 1 (MCP‐1)." (PMID 39554349, 2024). "To further verify our findings, we constructed DSS- and TNBS-induced colitis models by analyzing weight loss, colon length, DAI, and MPO." (PMID 37407995, 2023). "Importantly, FGF21 KO mice demonstrated an improved colitis score and reduced myeloperoxidase (MPO) activity compared to the WT mice." (PMID 37432218, 2023). "Furthermore, it reduced the activation of MPO, a factor associated with oxidative stress, in a DSS-induced colitis model, suppressing oxidative stress and macrophage infiltration." (PMID 37834221, 2023). "Moreover, FGR treatment inhibited oxidative stress and macrophage infiltration by decreasing MPO activity in the DSS-induced colitis model." (PMID 36829894, 2023). "The results revealed that L. plantarum, COS, and the synbiotics alleviated the symptoms of mice colitis and inhibited the changes in short-chain fatty acids (SCFAs), tumor necrosis factor-α (TNF-α), interleukin (IL)-1β, IL-6, IL-10, and myeloperoxidase (MPO) caused by DSS." (PMID 37297494, 2023). "Similarly, it has been shown that colitis symptoms (colon shortening, DAI, loss of appetite, and weight gain), decreased SOD, and increased MPO can be mitigated and that GPx and GR activities can be increased by administering grape pomace extract (GPE)." (PMID 37701897, 2023). "Myeloid knockout of HIF-1α ameliorated murine dextran sodium sulfate (DSS)-induced colitis while myeloid HIF-2α knockout aggravated colitis by increasing myeloperoxidase (MPO)+ and CD3+FoxP3+ T regulatory cell recruitment deep in the colon with no apparent differences in F4/80+ cell infiltration." (PMID 37124241, 2023). "In this study, the oxidative injury caused by colitis preceded the inflammatory damage, once the levels of MPO, TNF-α, and IL-10 did not change." (PMID 37577725, 2023). "Oral administration of OA in a mice model of colitis significantly inhibited colon shortening and myeloperoxidase activity, displayed potent anti-inflammatory properties by reducing the activation of TNF-α, IL-1β, IL-17, NF-κB, and MAPK, and increasing the expression of IL-10." (PMID 36829984, 2023). "Our analysis showed that Butyricimonas had a negative correlation with proinflammatory cytokines, such as TNF-α and MPO, indicating that it may be effective in the progression of colitis." (PMID 37047694, 2023). "DSS-induced colitis can enhance the activity of myeloperoxidase (MPO) and malondialdehyde (MDA), reduce GSH, and downregulate gut microbiota diversity, whereas quercetin administration can attenuate oxidative stress in the intestinal tract and increase gut microbial diversity." (PMID 37107341, 2023). "Treatment with AA147 ameliorated DSS-induced colitis in Pcdh20 CKO mice, characterized by less weight loss, lower DAI, longer colon length, lower levels of pathological scores, and lower MPO activity in colonic tissue than those in PBS-treated Pcdh20 CKO mice with colitis." (PMID 37407995, 2023). "Among many proinflammatory mediators, myeloid oxidase (MPO) is positively correlated with the severity of colitis, alkaline phosphatase (ALP) is closely related to the degree of colonic tissue inflammation, and glutathione (GSH) reflects colonic tissue antioxidant level." (PMID 36840499, 2023). "MPO activity in a colitis-induced mice experiment decreased with COST administration." (PMID 37736519, 2023). "For tissue level homogenate oxidative stress markers (MDA and MPO), there were highly significant increases in the colitis group (7.47±1.21 ng/ml and 250.4±30.27 pg/ml, respectively) compared to the healthy control group (1.37±0.39 ng/ml and 105.70±19.70 pg/ml, respectively)." (PMID 38024826, 2023).
colitis (continued). "(100, 300 mg/kg) could improve the syndrome of TNBS-induced colitis mice by regulating the MPO and MDA contents and the levels of pro-inflammatory (TNF-α, IL-6, L-1β, IL-12, IFN-γ, IL-2, IL-17) cytokines and anti-inflammatory cytokines (IL-4, IL-10)." (PMID 36160392, 2022). "Likewise, RvE1 facilitated tissue repair in peritonitis mice with TNBS-colitis, while significantly reduced the leukocyte infiltration, MPO activity, and the expression of genes corresponding to pro-inflammatory response (COX-2, TNF-α, IL-12p40, iNOS)." (PMID 35399093, 2022). "In conclusion, our results revealed that oral administration of BCP in DSS-induced ulcerative colitis mice improved colitis by reducing MPO activity, IL-1β, IL-6, and TNF-α concentrations, as well as the abundance of bacteria that cause intestinal immune imbalance." (PMID 36431883, 2022). "Furthermore, sulfasalazine and hFm alleviated cGm-induced colitis: they suppressed myeloperoxidase activity, IL-1β and IL-6 expression and increased IL-10 expression." (PMID 35631220, 2022). "The results showed that L. gasseri JM1 and mesalazine could significantly reduce inflammation in mice with colitis by decreasing serum MPO activity to varying degrees." (PMID 36615796, 2022). "In the present study, except for the obvious UC symptoms, we observed an increase in pro-inflammatory cytokines (TNF-α, IL-6) and MPO activity as well as a decrease in anti-inflammatory cytokines such as IL-10, which are closely related to the severity of colitis." (PMID 36295859, 2022). "TPGS-PBTE NPs could reduce the ROS concentration and MPO amount in colitis tissue, and promote GSH concentration, thus rebuilding antioxidant/oxidation balance in the colons." (PMID 35372817, 2022). "Carvacrol (50 mg) before and after tumor induction increased anti‐oxidant enzymes such as catalase, superoxide dismutase, and glutathione levels, reduced (myeloperoxidase, lipid peroxides, and nitric oxide), and restored the histological lesions in the colitis." (PMID 36348778, 2022). "Furthermore, the HEBD increased the antioxidant defenses in the colon and hippocampus and reduced the myeloperoxidase activity and IL-6 levels in the colon from colitis mice." (PMID 35295931, 2022). "HO treatment at a dose of 40 μg/kg significantly attenuated DSS-induced colitis in mice, as demonstrated by reducing body weight change, macroscopic scores (p < 0.0001), and histological scores (p = 0.0001), as well as colonic MPO activity (p = 0.0045), which were inhibited by pretreatment of NH." (PMID 36176442, 2022). "They found that a plant-based diet could significantly reduce MPO activity and IgE content as well as increase IgA content in colitis." (PMID 36451737, 2022). "Exacerbated colitis, aggravated changes in colon length, MPO, TNF-α and IL-1β in gut tissue." (PMID 35893902, 2022). "The results showed that exogenous ghrelin increased the activity score of colitis, neutrophil infiltration in the colon and the expression of IL-1β, as well as the myeloperoxidase activity of colonic tissue in ghrelin-treated colitis mice compared with saline-treated colitis mice." (PMID 35050153, 2022). "Unexpectedly, the CO-fed diet had weak staining for MPO+ cell infiltration compared to the other diet groups despite showing more ulcerations and more severe colitis, which suggests other intestinal responses besides neutrophils are driving colonic damage, although we did not rule out netosis." (PMID 35471119, 2022). "In addition, Forsythia suspensa extract reduced oxidative stress and MPO activity to alleviate colitis." (PMID 35326124, 2022). "The results indicated that all inflammation parameters, including the tissue wet weight index (WWI), histological score and myeloperoxidase (MPO) activity, increased in colitis rats in comparison with the control group; however, CCK-8 decreased these parameters." (PMID 35050153, 2022).
colitis (continued). "Furthermore, orally gavaged or intraperitoneally injected buspirone alleviated colitis: it reduced myeloperoxidase activity, TNF-α and IL-6 expression, and NF-κB+/CD11c+ cell population." (PMID 33731795, 2021). "However, CSS treatment alleviated the RS-induced colitis: it inhibited colon shortening, suppressed myeloperoxidase activity and NF-κB activation (p-p65 to p65 ratio), and decreased IL-6 expression." (PMID 34391441, 2021). "TQ treatment also reduced inflammation in acetic acid-induced colitis in rats, with inhibition of the myeloperoxidase activity, platelet-activating factor (PAF), and histamine, together with prevention of glutathione (GSH) depletion, suggesting that inhibition of oxidation was involved." (PMID 33920708, 2021). "Besides the effects of UAMC-00050 on colonic compliance, a small but significant increase in MPO activity was seen in colonic tissue samples of both post-colitis and control rats." (PMID 34072320, 2021). "Meanwhile, the activity of MPO is also an important biomarker of neutrophils infiltration into the inflamed colonic tissue, which is commonly used to evaluate the severity degree of colonic inflammation in kinds of experimental studies and clinical trials." (PMID 34956390, 2021). "Results of MPO activity detection showed that MPO activity was significantly increased in the DSS-induced colitis mice, which was obviously inhibited by treatment with cinacalcet, and immunofluorescence staining of macrophages suggested that cinacalcet also reduced macrophage infiltration." (PMID 34880751, 2021). "Moreover, oral gavage of ampicillin induced colitis: it increased colon shortening, myeloperoxidase activity, and IFN-γ and TNF-α expression and reduced IL-10 expression in the colon." (PMID 34667205, 2021). "Additionally, BMP noticeably ameliorated colitis symptoms, and improved colonic infiltration by reducing the levels of MPO and EPO in the colonic tissue." (PMID 33981232, 2021). "The MPO activity was significantly higher in colon tissues isolated from the animals from untreated colitis, CsAc, and CsAc-AMP-treated groups than in the animals of healthy control group; this indicated that inflammation did not improve following treatment with CsAc and CsAc-AMPs." (PMID 34575488, 2021). "Importantly, OXY decreased MPO activity, which confirmed the former’s therapeutic effect in colitis." (PMID 33946346, 2021). "Finally, we demonstrated that a single dose of orally administered GLUPEA was as efficacious as the same dose of PEA-um at reducing the colon weight/colon length ratio and MPO activity in DNBS-induced colitis in mice." (PMID 33672574, 2021). "However, oral gavage and intraperitoneal injection of buspirone alleviated IS-induced colitis: it suppressed myeloperoxidase activity, IL-1β, IL-6, and TNF-α expression, and NF-κB+/CD11c+ cell population in the colon." (PMID 33731795, 2021). "The notable inflammatory response that accompanies induced colitis was confirmed by a significant increase in myeloperoxidase (MPO) activity (7- and 2-fold higher than PBS-L. lactis-WT and DSS-L. lactis-WT mice, respectively, p < 0.001 and p < 0.05), a marker for tissue neutrophil content." (PMID 34685638, 2021). "Moreover, an olive oil-based diet with fish oil supplementation for 2 weeks before colitis induction with dextran sodium sulfate decreased MPO activity in colon." (PMID 33673609, 2021). "However, treatments with buspirone suppressed EC-induced colon shortening, myeloperoxidase activity, and NF-κB activation in the colon, resulting in the attenuation of colitis." (PMID 33731795, 2021). "Moreover, in vivo screening, performed in an oxazolone-induced colitis rat model, showed that the formulation significantly reduced the clinical signs of disease, colonic MPO action and pro-inflammatory cytokine panel." (PMID 34443866, 2021). "However, the administration of sinapic acid significantly reduced the generation of MPO in the colons of colitis mice." (PMID 33312339, 2020).
colitis (continued). "In addition, in a colitis model in iNOS KO mice, inflammation and elevated MPO activities persisted at 2 weeks compared to control mice, which improved colitis and decreased MPO activity." (PMID 33281627, 2020). "LP-YS4 could markedly attenuate the decline in GSH and SOD levels and prevented colitis-induced increase in MPO and MDA levels (P < 0.05)." (PMID 32849906, 2020). "Overall, AZD3241 ameliorated the course and severity of experimental colitis through ameliorating MPO derived tissue damage and could be considered a potential therapeutic option, subject to further validation in chronic IBD models." (PMID 33041796, 2020). "Furthermore, increased infiltration and migration of MPO positive neutrophils into the colon tissue and an increased gene expression of Ly6g in HIF-2α deficient animals during DSS-induced colitis was evident." (PMID 33202783, 2020). "Thus, measuring MPO activity in colitis tissue is an effective method to estimate the extent of neutrophil infiltration." (PMID 33092149, 2020). "As an irritant agent, AA induces the colitis involving infiltration of colonic mucosa with neutrophils and increased production of inflammatory mediators, such as hydrogen peroxide, nitric oxide (NO), myeloperoxidase, and TNF-α." (PMID 32074166, 2020). "Since the increased production of TNF-α and the infiltration of neutrophils have been described as key factors in the inflammatory damage observed in DSS-induced colitis, we evaluated the colon MPO activity as an indirect marker of neutrophil infiltration and the concentration of colon TNF-α." (PMID 33042131, 2020). "In this study, we found that DSS significantly increased the colonic levels of MPO in colitis mice." (PMID 33312339, 2020). "We further found uvaol could attenuate disease activity index (DAI), colon shortening, colon injury, and colonic myeloperoxidase activity in DSS-induced colitis mice." (PMID 32411289, 2020). "Colonic MPO was increased in DSS colitis mice statistically." (PMID 32650602, 2020). "Free F96 ameliorated DSS-induced colitis, lowered the MPO activity and restored mucosal damage." (PMID 35519029, 2020). "Apigenin decreased myeloperoxidase (MPO), inflammatory cytokine and COX-2 levels and downregulated NF-κB and STAT3, thereby inhibiting inflammation and inflammation-induced carcinogenesis in an inflammatory bowel disease and colitis-associated cancer model." (PMID 32059369, 2020). "Furthermore, treatment with RG or fRG suppressed the stress-induced colitis: they suppressed myeloperoxidase activity, NF-κB activation, and NF-κB+/CD11c+ cell population in the colon." (PMID 32224881, 2020). "Overall, these findings showed that bilobalide could effectively relieve symptoms of colitis effectively in mice like bloody diarrhea and MPO expression in the acute phase of colitis in colonic tissue." (PMID 32670051, 2020). "There were significant differences in the colonic MPO concentrations among the three groups at d3 and d5 (F = 34.49, P < 0.001; F = 23.67, P < 0.001), and the colonic MPO concentrations in the colitis group were higher than those in the control group or pair-fed group (P < 0.01)." (PMID 31221091, 2019). "In a rat model of TNBS-colitis, treatment with curcumin significantly reduced activity of MPO." (PMID 31003422, 2019). "Regarding neutrophils accumulation and activity, similar to TNBS-induced colitis, in this study we showed that T. gondii-induced ileitis also triggers innate immune mechanisms, including increased myeloperoxidase activity, in addition to potential effects on the adaptive immune response." (PMID 30936867, 2019). "Additionally, in a rat methotrexate-colitis model, curcumin decreased intestinal MPO and increased levels of free radical-scavenging superoxide dismutase (SOD)." (PMID 31003422, 2019). "Indeed, macroscopic and histologic scores and myeloperoxidase activity were higher in colitis mice exposed to aluminum." (PMID 31109097, 2019).